CHMP4B (charged multivesicular body protein 4B)
Description:
Probable core component of the endosomal sorting required for transport complex III (ESCRT-III) which is involved in multivesicular bodies (MVBs) formation and sorting of endosomal cargo proteins into MVBs. MVBs contain intraluminal vesicles (ILVs) that are generated by invagination and scission from the limiting membrane of the endosome and mostly are delivered to lysosomes enabling degradation of membrane proteins, such as stimulated growth factor receptors, lysosomal enzymes and lipids. The MVB pathway appears to require the sequential function of ESCRT-O, -I,-II and -III complexes. ESCRT-III proteins mostly dissociate from the invaginating membrane before the ILV is released. The ESCRT machinery also functions in topologically equivalent membrane fission events, such as the terminal stages of cytokinesis. Together with SPAST, the ESCRT-III complex promotes nuclear envelope sealing and mitotic spindle disassembly during late anaphase. Plays a role in the endosomal sorting pathway. ESCRT-III proteins are believed to mediate the necessary vesicle extrusion and/or membrane fission activities, possibly in conjunction with the AAA ATPase VPS4. When overexpressed, membrane-assembled circular arrays of CHMP4B filaments can promote or stabilize negative curvature and outward budding. CHMP4A/B/C are required for the exosomal release of SDCBP, CD63 and syndecan. Majority of the protein exists in a folded closed conformation. (Microbial infection) The ESCRT machinery also functions in topologically equivalent membrane fission events, such as the budding of enveloped viruses (HIV-1 and other lentiviruses). Via its interaction with PDCD6IP involved in HIV-1 p6- and p9-dependent virus release.
Synonyms: Vps32-2; C20orf178; SHAX1; dJ553F4.4; SNF7-2; VPS32B; CHMP4A; CTPP3; CTRCT31; SNF7
Tractability: Antibody: UniProt places it where antibodies can reach, with high confidence; its Gene Ontology location is reachable by antibodies, with high confidence. PROTAC: UniProt records ubiquitination sites on it; ubiquitination databases record sites on it; its protein half-life has been measured.
Gene: Protein-coding gene on chromosome 20 (33,811,345 to 33,854,366, forward strand). Ensembl gene ENSG00000101421.
Subcellular location: Cytoplasm, cytosol; Late endosome membrane; Midbody; Nucleus envelope
Pathways (Reactome):
Disease: Budding and maturation of HIV virion; HCMV Late Events; Translation of Replicase and Assembly of the Replication Transcription Complex
Autophagy: Late endosomal microautophagy; Macroautophagy
Cell Cycle: Sealing of the nuclear envelope (NE) by ESCRT-III
Programmed Cell Death: Pyroptosis
Vesicle-mediated transport: Endosomal Sorting Complex Required For Transport (ESCRT)
Gene Ontology:
Molecular function: cadherin binding; identical protein binding; protein binding; protein homodimerization activity
Biological process: autophagosome maturation; autophagy; endosome transport via multivesicular body sorting pathway; exit from mitosis; late endosome to lysosome transport; maintenance of lens transparency; membrane fission; midbody abscission; mitotic cytokinesis; mitotic metaphase chromosome alignment; multivesicular body sorting pathway; nervous system process; nuclear membrane reassembly; nucleus organization; plasma membrane repair; post-translational protein targeting to endoplasmic reticulum membrane; protein polymerization; regulation of centrosome duplication; regulation of mitotic spindle assembly; ubiquitin-dependent protein catabolic process via the multivesicular body sorting pathway; viral budding; viral budding from plasma membrane; viral budding via host ESCRT complex; late endosome to vacuole transport via multivesicular body sorting pathway; macroautophagy; and 4 more
Cellular component: amphisome membrane; autophagosome membrane; cytoplasm; cytoplasmic side of plasma membrane; endosome; ESCRT III complex; extracellular exosome; kinetochore; kinetochore microtubule; late endosome membrane; lysosomal membrane; membrane coat; midbody; multivesicular body membrane; nuclear envelope; nuclear pore; nucleus; plasma membrane; vesicle; cytosol
Genetic constraint (gnomAD): Loss-of-function variants: 1 observed, 22.84 expected, observed/expected ratio (o/e) 0.0438, 90% interval 0.015 to 0.21. The upper end of that interval is the gene's LOEUF score, 0.21, which puts it in group 1 of 6, group 1 being the genes least tolerant of losing a copy. Missense variants: 150 observed, 283.47 expected, observed/expected ratio (o/e) 0.53, 90% interval 0.46 to 0.61. Synonymous variants: 97 observed, 114.83 expected, observed/expected ratio (o/e) 0.84, 90% interval 0.72 to 1.
Homologues: Orthologues: chimpanzee CHMP4B (100% identical), macaque CHMP4B (100% identical), mouse Chmp4b (99% identical), rat Chmp4b (99% identical), dog CHMP4B (98% identical), rat Chmp4bl1 (97% identical), guinea pig CHMP4B (96% identical), tropical clawed frog chmp4b (87% identical), zebrafish chmp4ba (84% identical), zebrafish chmp4bb (83% identical), Caenorhabditis elegans vps-32.1 (61% identical), Drosophila melanogaster shrb (60% identical). Paralogues in human: CHMP4BP1 (69% identical), CHMP4C (66% identical), CHMP4A (62% identical), CHMP5 (29% identical), CHMP7 (25% identical).